IL6 (interleukin 6)
Diseases named in the same sentence as IL6 in open-access papers (continued):
Sharing a sentence is not in itself a finding about the gene and the disease.
lung carcinoma (continued). "The present study is the first to illustrate that LDOC1 functions as a bridge between tobacco smoke exposure and IL-6/JAK2/STAT3 activation in lung cancer." (PMID 30634502, 2019). "In summary, our findings reveal a reciprocal regulation of miR‐206 and IL‐6/STAT3 pathway that mediates IL‐6‐induced gefitinib resistance in EGFR‐mutant lung cancer cells." (PMID 31507089, 2019). "Production of IL-6 and IL-8 affect the growth and migration of lung cancer cells as it plays a potential role in cancer development." (PMID 31491033, 2019). "Recent studies have reported that lung cancer cell-derived exosomes can accelerate MSCs to release proinflammatory cytokines, such as IL-8 and IL-6, by activating NF-κB signaling of MSCs." (PMID 31428639, 2019). "The potent effects of miR‐206 in reducing the IL6‐induced gefitinib resistance in EGFR‐mutant lung cancer prompted us to explore the direct downstream effector of miR‐206." (PMID 31507089, 2019). "Previous studies have showed that IL-6 is involved in tumor progression and metastasis in various types of cancer, including lung cancer, pancreatic cancer, liver cancer, gastric cancer and colon cancer." (PMID 30744595, 2019). "The expression of miR-218 was found significantly downregulated in lung cancer tissues and it acted as a tumor suppressor in lung cancer by targeting IL-6/STAT3 and negatively correlated with poor prognosis." (PMID 31164163, 2019). "We showed that forced miR‐206 expression restored gefitinib sensitivity in IL6‐induced gefitinib‐resistant EGFR‐mutant lung cancer cells by inhibiting IL6/JAK1/STAT3 pathway." (PMID 31507089, 2019). "The IL-6—STAT3 signalling axis has emerged as a key contributor to carcinogenesis in a number of cancers, often resulting in increased IL-6 expression as observed in lung cancer and head and neck cancers." (PMID 31226168, 2019). "For example, EGFR activation in response to EGF binding mediates IL-6 production in ovarian and lung cancer cells." (PMID 31470515, 2019). "In solid tumour model, siltuximab, an IL-6 antibody, has demonstrated antitumor efficacy against ovarian, prostate, and lung cancers." (PMID 30744595, 2019). "Next, we examined the effects of IL-6 on lung cancer EMT and MMP expression regulation in differentiated ADSCs." (PMID 31196220, 2019). "In particular, the data revealed a novel regulatory mechanism of the IL-6/JAK2/STAT3 loop in the pathogenesis of lung cancer." (PMID 30634502, 2019). "A high dose of quercetin (66 μM) was found to reduce p-STAT3 levels in lung cancer cells after a long incubation period (12–24 h) by an indirect effect on NF-κB activation and IL-6 production." (PMID 31491838, 2019). "It has been reported that IL-6 signaling prevented CD133+ stem-like cells of lung cancer and was essential for the resolution of H1N1 influenza infection by promoting neutrophils survival." (PMID 32038632, 2019). "In sum, these data support that the intracellular IL‐6 serves as a direct target of miR‐206 in EGFR‐mutant lung cancer cells." (PMID 31507089, 2019). "Apparently, in many inflammatory diseases as well as in colon cancer and lung cancer, the IL-6 trans-signaling pathway plays a dominant role as compared to the TNFα signaling pathway." (PMID 31694340, 2019). "CAFs have also been shown to enhance the metastatic potential of lung cancers via IL-6/STAT3 signalling pathways." (PMID 31878245, 2019). "IL-6-expressing lung cancer cells are known to exist in human lung cancer tissues 51 and IL-6 has also been shown to play an important role in protecting NSCLC CD133+ cells from radiation-induced DNA damage and apoptosis." (PMID 31367260, 2019). "Treatment with CM from 4 different lung cancer cell lines for 48 h led to increased expression of Acta2, IL-6, IL-11 and LIF." (PMID 31196220, 2019).
lung carcinoma (continued). "Nevertheless, the decreased IκB and IL6 promoter methylation levels to regulate IL6 expression were observed only in lung cancer cells, implying different regulatory mechanism(s) controlling IL6 expression in M2 macrophages and lung cancer cells." (PMID 30266897, 2018). "There are different regulatory mechanisms controlling USP24-induced IL-6 expression in M2 macrophages and lung cancer cells." (PMID 30266897, 2018). "In a previous study, it was shown that MEK inhibition triggers STAT3 signaling via IL‐6 in lung cancer." (PMID 29896883, 2018). "Analysis of p300 and NF-κB levels in cancer cells showed that p300 but not NF-κB was decreased after USP24 knockdown, implying that there are distinct mechanism(s) regulating IL-6 expression in M2 macrophages and lung cancer cells." (PMID 30266897, 2018). "In this study, we studied the effect of USP24 in lung cancer malignancy through the USP24/p300/ NF-κB/IL-6 regulatory axis." (PMID 30266897, 2018). "In a cohort of patients bearing EGFR mutant lung cancers, increased peripheral natural killer cells and INFγ were observed after 4 weeks of gefitinib treatment while circulating IL6 levels were decreased, especially in those patients sensitive to gefitinib." (PMID 29458371, 2018). "Further studies demonstrated that CAFs enhanced the metastatic potential of lung cancer cells by secreting IL-6 and subsequently activating the JAK2/STAT3 signaling pathway." (PMID 30380628, 2018). "Because p300 was decreased in USP24-knockdown lung cancer cells, the histone H3 acetylation level in the IL-6 promoter was also examined after USP24 knockdown in A549 cells." (PMID 30266897, 2018). "Here, the authors demonstrate that USP24 stabilizes p300 and β-TrCP to increase the levels of NF-κB and histone-3 acetylation, and decrease DNMT1 and IκB levels which promotes IL-6 expression in M2 macrophages and lung cancer cells." (PMID 30266897, 2018). "Interleukin 6 (IL6) is a pleiotropic cytokine that plays an important role in multiple pathophysiological properties associated with cancer development, including lung cancer." (PMID 29970138, 2018). "IL-6 expression is significantly decreased in USP24-knockdown M2 macrophages and lung cancer cells, and IL-6-replenished conditioned medium restores the migratory, chemotactic and angiogenetic properties of the cells." (PMID 30266897, 2018). "For instance, chronic inflammation caused by IL-6 promoted the development colorectal cancer (CRC) and the metastasis of lung cancer." (PMID 30174788, 2018). "The detailed mechanisms regarding how USP24 regulates IL-6 expression in M2 macrophages and lung cancer cells require further clarification." (PMID 30266897, 2018). "The results showed that silencing USP24 in lung cancer cells decreased histone 3 acetylation at the IL-6 promoter region, implying that the transcriptional activity of IL-6 is inhibited by USP24 knockdown." (PMID 30266897, 2018). "Recently, HHT has been shown to induce apoptosis and suppress STAT3 via IL-6/JAK1/STAT3 signal pathway in Gefitinib-resistant lung cancer cells." (PMID 29788973, 2018). "Increased levels of IL-1 and IL-6 are noticed in lung cancer patients and progressively decrease as cancer progresses." (PMID 30365491, 2018). "CD10 and GPR77 expressing CAFs induce cancer stem cells in breast and lung cancer through the consistent secretion of IL-6 and IL-8." (PMID 30380628, 2018). "USP24 stabilizes p300 and β-TrCP to increase the levels of histone-3 acetylation and NF-κB, and decreases the levels of DNMT1 and IκB, thereby increasing IL-6 transcription in M2 macrophages and lung cancer cells, results in cancer malignancy finally." (PMID 30266897, 2018). "Recently, tocilizumab, a humanized recombinant mAb against the IL-6R, showed the potential to improve prognosis in IL-6-expressing lung cancer and recurrent epithelial ovarian cancer." (PMID 30083161, 2018).
lung carcinoma (continued). "Generally, the biological functions of IL-6 are achieved via the Janus kinases/STAT3 (JAK/STAT3) pathway that is frequently presented in cancers including lung cancer." (PMID 29416638, 2018). "Taken together, these results indicate that there is a positive feedback loop between IL6 and ERβ in lung cancer by an autocrine mechanism, where treatment with E2 induces IL6 expression." (PMID 29970138, 2018). "Considering both IL6 and aggressiveness of lung cancer cells up-regulation upon treatment with E2, meanwhile blocking IL6/Stat3 signal pathway reverse the effect." (PMID 29970138, 2018). "Our results highlight the possibility of a synergistic effect in treating lung cancers through a combination of ERβ and IL6 inhibitors." (PMID 29970138, 2018). "In this line, using an elegant cell culture model previously developed in the laboratory we were able to show that IL-6, G-CSF and Activin-A released by stromal fibroblasts drive lung carcinoma cells’ dedifferentiation and CSCs formation." (PMID 30069023, 2018). "On the other hand, it was also shown that the IL‐6/JAK/STAT3 signaling pathway‐mediated PD‐L1 increase in lung cancer cells was via activation of EGFR‐tyrosine kinase." (PMID 28865178, 2018). "To identify the relationship between IL6 and ERβ in NSCLC, we performed IHC and found that ectopic expression of IL6 and ERβ were both significantly increased in malignant lung cancer, indicating a correlation between IL6 and ERβ in lung cancer." (PMID 29970138, 2018). "In this study, another interesting point is the discovery of distinct molecular mechanisms regulating IL-6 expression in M2 macrophages and lung cancer cells in response to USP24." (PMID 30266897, 2018). "This holds particular importance as connection to circulating IL-6 and IL-8 was previously reported in lung cancer, but also to intestinal SCFA concentrations." (PMID 30558074, 2018). "In association with elevated USP17 expression, the levels of inflammatory mediators, including IL-1β, IL-6, and IL-8 were increased in lung cancer samples." (PMID 30038267, 2018). "We found that interleukin-6 (IL-6), which was expressed in the lung induced CSCs, facilitates the formation of lung cancer organoids via the conversion of mesenchymal stem cells into alpha-smooth muscle actin (αSMA)-positive cells." (PMID 28951614, 2017). "A few previous reports that showed the production of IL-6 by cultured cancer cells support our present findings which demonstrated the expression of IL-6 in the induced lung CSCs and a small number of the cancer cells in bona fide human lung cancer tissues." (PMID 28951614, 2017). "The mechanistic study demonstrates that IL-6/STAT3 signaling pathway mediates the enhanced effect of CAFs on lung cancer cells metastasis potential." (PMID 29100297, 2017). "Our study has demonstrated that Pir-B inhibits the DC function and disturbs the Th17/Treg balance via IL-6 pathway during the progression of lung cancer, contributing to inhibited antitumor immunity." (PMID 29383114, 2017). "IL-6 enhanced the migration of lung cancer cells, and IL-6 neutralizing antibody abolished the effect of CAF-CM on cell migration." (PMID 29100297, 2017). "The lung cancer organoids that were established in the present study provide complementary evidence to support the efficacy of IL-6-targeted therapy and strengthen the rationale for a clinical trial of the therapy." (PMID 28951614, 2017). "Recent work on a small panel of circulating cytokines identified elevated levels of IL-6, a pro-inflammatory cytokine, as an indicator of poor survival in lung cancer patients." (PMID 28402963, 2017). "Findings from recent studies have indicated that the expressions of CSC markers are significantly upregulated in IL-6 expressing lung cancer cells and cell-derived tumor xenograft tissues after cisplatin treatment." (PMID 28878571, 2017).
lung carcinoma (continued). "The mechanism study showed that IL-6/STAT3 signaling pathway mediated the enhanced effect of CAFs on lung cancer cell metastasis." (PMID 29100297, 2017). "Thought to be involved in the modulation of the radiation-induced PD-L1 increase and NKG2D ligands decrease in lung cancer cells after radiation, we studied the implication of IL-6 signaling based on our several previous findings." (PMID 29113321, 2017). "Recent work on a small panel of circulating cytokines identified elevated levels of IL-6, a pro-inflammatory cytokine, as an indicator of poor survival for lung cancer patients." (PMID 28402963, 2017). "This suggests that the production of IL-6 by lung CSCs and the consequent high IL-6 concentration just around the lung CSCs is important for the construction of lung cancer tissue." (PMID 28951614, 2017). "IDO was demonstrated to drive IL-6 production in lung cancer and metastatic breast cancer (Lox-Stop-Lox KrasG12D transgenic mice), while IL-6 was confirmed to promote IDO expression via JAK/STAT signaling pathway." (PMID 29296206, 2017). "We also found that IL-6 signaling was involved in rendering radioresistance of lung cancer cells by promoting DNA repair after irradiation." (PMID 29113321, 2017). "Taken together, these results demonstrated that CAFs induced EMT and enhanced the metastasis potential of lung cancer cells by secreting IL-6." (PMID 29100297, 2017). "In the present study, IL-6 secreted by DCs was decreased during the progression of lung cancer, and this was accompanied by the decreased response of Th17 cells and the increased differentiation of Tregs." (PMID 29383114, 2017). "This analysis demonstrated that there is a significantly shorter overall survival for lung cancer patients with IL-6 mRNA levels above the median value (HR = 1.32, longrank p = 1.7e-05, n = 1926)." (PMID 28515477, 2017). "Taken together, these results demonstrate that loss of ING5 enhances aggressiveness of lung cancer cells by promoting EMT via activation of EGFR/PI3K/Akt and IL-6/STAT3 signaling pathways." (PMID 28903339, 2017). "In the present study, the DC function and Th17/Treg balance are impaired during the progression of lung cancer, and Pir-B is involving in inhibiting the DC function and Th17 response and promoting Treg differentiation via IL-6 pathway." (PMID 29383114, 2017). "The previous evidence has confirmed the potential regulation role of TGFB on these genes, such as EGR1, EGFR, and IL6 in the lung cancer." (PMID 28959347, 2017). "6-OAP inhibited constitutively activated STAT3, suppressed IL-6-induced pSTAT3, and triggered apoptosis and suppressed migration of lung cancer cells in vitro and showed potent anti-lung cancer activity in vivo." (PMID 27835873, 2017). "In lung cancer patients, were cachexia is prevalent, there was a significant correlation between elevated IL-6 expression in the tumor and poor prognosis of the patients." (PMID 28515477, 2017). "Pir-B impaired the DC function and disturbed the Th17/Treg balance via IL-6 pathway during the progression of lung cancer, contributing to tumor related immunosupression." (PMID 29383114, 2017). "In order to confirm these results, one strategy we used was to block IL-6 by preincubating CAF-CM with 5 μg/ml of IL-6 neutralizing antibody for 4 h, then cultured with lung cancer cells." (PMID 29100297, 2017). "Taken together, these findings revealed a novel mechanism that CAFs induced EMT and promoted metastasis of lung cancer cells through the IL-6/STAT3 signaling pathway." (PMID 29100297, 2017).
lung carcinoma (continued). "Some previous study indicated that IL-6/STAT3 signal was required for TGF-β-induced EMT process in lung cancer cells, and the crosstalk between the IL-6/STAT3 and TGF-β/p-SMAD3 signaling pathway did exist in certain conditions." (PMID 27992365, 2017). "In previous investigations, we observed significant increase of IL-6 level in lung cancer cells after radiation treatment, which was matched with the earlier report showing the radiation-induced IL-6 level increase in lung cancer cells." (PMID 29113321, 2017). "We also found that IL-6 mRNA-positive cancer cells actually exist in clinical lung cancer tissue samples." (PMID 28951614, 2017). "IDO was demonstrated to drive IL-6 production in lung cancer and metastatic breast cancer, while, downstream product of IDO metabolism, kynurenic acid, can potentiate IL-6 production by the aryl hydrocarbon receptor (AHR)." (PMID 29296206, 2017). "The addition of IL-6 (10 ng/ml) strengthened the lung cancer organoid construction ability of the parental A549 cells." (PMID 28951614, 2017). "Our study has demonstrated that Pir-B inhibits the DC function and disturbs the Th17/Treg balance via IL-6 pathway, contributing to inhibited antitumor immunity of lung cancer." (PMID 29383114, 2017). "Our data is supported by previous studies in gastric and lung cancer showing that cancer cell exosomes are able to elevate IL-6 secretion of transformed CAFs from MSCs." (PMID 29333170, 2017). "Further mechanistic studies demonstrated that CAFs enhanced the metastatic potential of lung cancer cells by secreting IL-6, subsequently activating of JAK2/STAT3 signaling pathway." (PMID 29100297, 2017). "Expression of Ahr expression requires binding of the NF-κB subunit, RelA (p65), and it has been shown to modulate the expression of genes, including Il6 in the context of lung cancer." (PMID 29051223, 2017). "For example, the aberrant TGF-β and interleukin-6 (IL-6) axis was reported to mediate selective and adaptive mechanisms of resistance to molecular targeted therapy in lung cancer." (PMID 27888618, 2017). "Through the use of these technologies and the evaluation of clinical samples, we identified interleukin-6 as a novel potential therapeutic target for lung cancer stem cells." (PMID 28951614, 2017). "Collectively, these findings indicated that CAFs induced EMT and enhanced the metastasis potential of lung cancer cells by activation of IL-6/STAT3 signaling pathway." (PMID 29100297, 2017). "Previous studies have demonstrated that IL-6 induces in vivo tumor growth in prostate, breast, and lung cancers, and that elevated IL-6 levels stimulate development of inflammation-associated cancers." (PMID 27852059, 2016). "Until now, most of the interest in cytokines in lung cancer has focused on IL-6, a proinflammatory cytokine that is upregulated in lung cancer patients and correlates with decreased cancer survival." (PMID 27445423, 2016). "IL-6 plays an essential role and has the specificity to regulate the nature of inflammation in lung cancer microenvironment and has tumor-promoting actions." (PMID 27095254, 2016). "To better explore the potential association and interaction mechanisms between IL-6 and EMT in lung cancer cells, we stimulated A549 with IL-6 in vitro cell culture." (PMID 27095254, 2016). "Nude mice were subcutaneously inoculated with cells of the IL-6–producing human lung cancer cell line LC-06-JCK and assessed as a model of cancer-related anemia." (PMID 27068103, 2016). "MR16-1, a rodent analog of tocilizumab, exhibited a dramatic effect on cachexia induced by an IL-6–overexpressing lung cancer." (PMID 26840088, 2016). "Recently, we demonstrated that IL-6 is critical for lung cancer metastasis and chemotherapeutic resistance." (PMID 27556690, 2016). "ATM, an upstream regulator of NF-κB, play a critical role in IL-6 increasing lung cancer metastasis and chemotherapeutic resistance." (PMID 27556690, 2016).